IGF1R (insulin like growth factor 1 receptor)
Diseases named in the same sentence as IGF1R in open-access papers (continued):
Sharing a sentence is not in itself a finding about the gene and the disease.
cancer (continued). "Illuminating the mechanisms of IGF-1R trafficking and endosomal sorting would provide new insights on IGF signaling in normal cells and cancer cells, and may also identify potential co-targets for pharmacological intervention in cancer." (PMID 33584548, 2020). "This may indicate that IGF1R-targeting strategies could benefit from additive effects with irradiation, platinum or PARP-based treatment–especially earlier in the clinical course of cancer." (PMID 32701997, 2020). "Affibody molecules binding specifically to several cancer relevant cell surface receptors have been generated, including epidermal growth factor receptor (EGFR), HER2, human epidermal growth factor receptor 3 (HER3), insulin-like growth factor 1 receptor (IGF1R), and carbonic anhydrase IX (CAIX)." (PMID 32344762, 2020). "While uncovering antagonism between the β-arrestin isoforms in controlling IGF-1R downregulation, it was demonstrated that biasing the IGF system toward β-arrestin 2 decreases the viability and the metastatic potential of cancer cells and hence could be considered an effective therapeutic strategy." (PMID 31600876, 2019). "As a result, no IGF-1R mAB or TKI is licensed for use in patients with cancer." (PMID 31416218, 2019). "Further investigation was necessary to detect whether the negative modulation of miR-505 on the expression of IGF-1R still occurs in other types of cancers." (PMID 31160483, 2019). "For these reasons, IGF1R was promoted as the Achilles’ heel of most, if not all, cancers." (PMID 29644076, 2018). "The role of IGF1R in the development and function of the immune system appears to be complex and variable; nonetheless, there is compelling evidence that within a TME, the IGF axis promotes an immunosuppressive, anti-inflammatory response that enables cancer growth." (PMID 29922232, 2018). "Interestingly, all four target genes were covered, or at least partially covered, by the five signaling pathways identified: BCL2L1 and IGF1R are involved in PI3K-Akt signaling, IGF1R and MAPK8 in FoxO signaling, IGF1R and FAS in proteoglycans in cancer, and MAPK8 and FAS in MAPK signaling." (PMID 30497474, 2018). "In vitro and in vivo studies revealed that let-7c negatively regulated cancer cell proliferation, migration, and epithelial-mesenchymal transition (EMT) via dysregulation of its direct target genes, insulin-like growth factor 1 receptor (IGF1R), and the high mobility group AT-hook 2 (HMGA2)." (PMID 30340457, 2018). "Also, the cluster with IGF1R and IGF2R in module 4 may also be useful for prognostic biomarkers in five cancers." (PMID 28676692, 2017). "The present study was aimed at evaluating the hypothesis that nuclear IGF1R localization is not restricted to cancer cells and might constitute a novel physiologically relevant regulatory mechanism." (PMID 28945762, 2017). "Although some of the signaling proteins downstream of IGF1R, such as Akt, mTOR and AMP-activated protein kinase (AMPK), have a pivotal role in cancer cell metabolic reprogramming, the possible role of IGF1R as a mediator of the Warburg effect has not been clearly established." (PMID 28969033, 2017). "Nevertheless, we still recommend the rest trials should be followed up in time, so that more precise conclusion that whether anti-IGF-1R-mAbs behave good as anti-cancer agents or not could be updated." (PMID 28427155, 2017). "Therefore exposure to an IGF-1R inhibitor such as BMS-754807 could delay DNA damage repair and therefore ‘prime’ cancer cells for treatment with a DNA damaging agent." (PMID 27472395, 2016).
cancer (continued). "Growth and survival of B-Raf(V600E) cancers is driven by B-Raf(V600E)-activated MAPK, as well as by a variety of de-repressed RTKs and transduction pathways that resist B-Raf(V600E) kinase inhibitors, including ErbB members, IGF1R, c-Met, IRS/PI3K/Akt/mTORC1, C-Raf/MEK/MAPK, Jak/STAT3 and/or c-Src." (PMID 26959890, 2016). "Recently, miR-375 has been found to suppress core hallmarks of cancer by targeting several important genes like AEG-1, YAP1, IGF1R and PDK1.The target genes regulated by miR-375 may function spatiotemporally or in cooperation with each other in different cellular processes." (PMID 26642205, 2015). "Our work elucidates the mechanisms of HER-1/IGF-1R and HER-1/HER-2 signaling in these cancer cell lines, and the promising results support the rationale for dual targeting with HER-1 and HER-2 or IGF-1R as an improved treatment regimen for advanced therapy tailored to difference types of cancer." (PMID 26350593, 2015). "Consistent with expectations, canonical luminal genes such as ESR1, GATA3, FOXA1, TFF1 and IGF1R were higher in ER+ samples compared to triple negative samples, while proliferation and mesenchymal genes such as SPRY2, SNAI2, FOSL1, MET and BUB1 were higher in triple negative cancers." (PMID 24520381, 2014). "However, whereas the IGF1R has been identified as a potential therapeutic target in cancer, such a validation is still lacking for the closely related INSR." (PMID 24434591, 2014). "This suggests that high surface expression of IGF1R may not be a requirement for response to anti-IGF1R therapy and the antibody may work via additional, undiscovered mechanisms to inhibit cancer cell proliferation." (PMID 25170759, 2014). "Taken together, the observation of let-7d-5p/3p and multiple-miRNA targeting of IGF1R and KRAS is consistent with the safe-proof mechanism of miRNA regulation of crucial factors in cancer-related pathways to warranty continued advantages in the promotion and maintenance of the cancer phenotype." (PMID 25287248, 2014). "Distrupting IGF-1R signaling alone may not be effective in inhibiting progression of some cancer types." (PMID 23675509, 2013). "The low-level activation induced by ganitumab in the Balb/C 3T3 hIGF1R and 32D hIGF1R/IRS-1 cells appeared to be specific to cells that overexpress IGF1R, since it could not be reproduced in other human cancer cell lines." (PMID 23383308, 2013). "Similarly to KIT, PDGFRA and their ligands, insulin-like growth factor (IGF)-1 receptor (IGF1R), a type 2 RTK, and its ligands IGF1 and IGF2 play critical roles in normal growth and development, as well as in cellular stress, aging and cancer by stimulating protein synthesis and the cell cycle." (PMID 24116170, 2013). "There might be an interaction between cancer cells and stromal cells via IGF/IGF1R signaling." (PMID 23962053, 2013). "Combining the current EGFR assay in a multiplex fashion with similar assays for IGF-1R and cMet could provide for optimal therapeutic choice and a drug resistance biomarker panel to drive targeted therapeutic efforts in NSCLC, as well as other cancers." (PMID 22554165, 2012). "Without post-translational NLG modification of the IGF1R at this site, IGF1R/IR HRs apparently fail to localize to the plasma membrane, thus preventing receptor-ligand binding and decreasing the efficacy of anti-IGF1R antibody-based cancer therapies." (PMID 22438913, 2012). "Thus IR inhibition in cancer celllines (LCC6 and T47D) causes reduced Akt activation by insulin, with no involvement ofthe IGF-1R." (PMID 23908801, 2011).
cancer (continued). "Proliferation of the carcinoma cell line H358, which exhibited a moderate activation of the HER1, HER2, and IGF-1R pathways, was weakly blocked by the HER1/2 inhibitors, Lapatinib and Gefitinib, but the IGF-1R inhibitor BMS-536924 was able to inhibit its proliferation more effectively." (PMID 22091388, 2011). "Inhibition of IGF-1R abrogated rapamycin-induced phospho-Akt induction and substrate phosphorylation, and combination of rapamycin with an inhibitor of IGF-1R had additive effects on proliferation irrespective of PTEN status and increased apoptosis in a PTEN mutant cancer cell line." (PMID 16953237, 2006). "This suggests that while IGF-1R can be a valid target in ATC cells because of its location, it may work better when combined with other therapeutic agents, such as BRAF or MEK inhibitors, to improve patient outcomes, as demonstrated with other types of cancer, such as melanoma." (PMID 40071065, 2025). "However, it is not clear how IGF-1R controls STAT3 activation in cancer." (PMID 39638246, 2024). "But our understanding of the IGF-1R signaling cascade, its interplay with other cellular signaling pathways, and non-canonical functions of IGF-1R has now reached the point where a re-examination of IGF-1R as a target for cancer therapeutics could be productive." (PMID 37858153, 2023). "Similarly, increased IGF-1R phosphorylation and activation upregulated MMP and ADAM expression and increased in parallel with increased sE-cad, activating the downstream ERK1/2 and PI3K/AKT signaling pathways, thus forming a positive feedback loop to promote cancer development." (PMID 37760996, 2023). "Various studies demonstrated that the impressive anti-cancer effects could be achieved by inhibition of RTKs such as human epidermal growth factor receptor 2 (HER2), mesenchymal epithelial transition factor (c-MET), insulin-like growth factor 1 receptor (IGF1R) and many others." (PMID 35372044, 2022). "However, in that study neither HI or IX10 stimulated the growth of the cancer cell xenografts, and it was therefore not possible to conclude whether increased binding affinity to the IGF-1R correlated with increased growth or not." (PMID 32350367, 2020). "Moreover, the presence of the IGF-1R at the Golgi may have potential to identify cancer subtypes where membrane targeting would not be effective." (PMID 33584548, 2020). "Therefore, E-cadherin expression in cancer cells with no or low migratory capacity may limit IGF-1R translocation to the Golgi apparatus." (PMID 33584548, 2020). "In turn the aberrant IGF1R-signaling favors the generation of primitive cancer stem cells and EMT, whereas IGF1R-inhibitors can revert these phenomena, thus, targeting IGF1R may have the potential to prevent hypoxia-induced cancer progression, EMT and ultimately TKI-resistance." (PMID 31266248, 2019). "However, murine embryos lacking IGF-1R do not develop cancer when exposed to oncogenes." (PMID 30111747, 2018). "However, more studies showed IGF-1R mono-antibodies had no significant value in cancer treatment." (PMID 28427155, 2017). "The mechanisms by which metformin affects cancers are also unknown, although a large number of publications have shown that metformin could exert its antitumor effect by targeting AMPK/mTOR, anti-inflammatory, cell cycle/apoptosis, insulin/IGF-1R, and angiogenesis pathways in cancers." (PMID 27517917, 2016). "In contrast to our analysis, a prior model of this system in cartilage suggested the IGF2R might play a role in regulating IGF2 interactions with IGF1R; however, these findings were not confirmed experimentally and were not seen in our model utilizing data from cancer cells." (PMID 26861122, 2016).
cancer (continued). "In addition to the EGFR, the insulin-like growth factor-1 receptor (IGF1R) is a major regulator of Akt activation and cross-talk between IGF1R and EGFR or EGFR family members such as Her2 has been reported as a mechanism of resistance against drugs targeting EGFR or Her2 in several types of cancers." (PMID 22815959, 2012). "Furthermore, we summarise the importance of the regulatory IGF/INS network in cancer, and discuss the possibilities and limitations of therapies targeting the IGF/INS axis with reference to ongoing clinical trials concerning the blockage of IGF1R in several types of cancer." (PMID 20924377, 2010). "In addition to its direct involvement in cancer cell survival and proliferation, the IGF1/IGF1R axis is also appearing as a key factor involved in the regulation of immunity and may be an important player in modulating the immune-compartment of the TME, and thus, the cancer-related immune response." (PMID 38420122, 2024). "Staining for other growth factor receptors revealed a high fraction of HGF-R-positive (>mean 47.92%: 14 out of 25, 58.33%) and IGF1-R-positive (>mean 52.08%: 12 out of 24, 50.00%), but not EGF-R-positive (>mean 17.08: 6 out of 24, 25.00%) cancer cells." (PMID 35565408, 2022). "Thus, scLCDV1-VILP is a natural peptide with specific antagonist properties on IGF1R signaling and may provide a new tool to guide development of hormonal analogues to treat cancers or metabolic disorders sensitive to IGF-1 without affecting glucose metabolism." (PMID 36335114, 2022). "The interrelated roles of IGF1R inhibition and TLR9/autophagy signaling in HT29 cancer cells have not yet been clarified." (PMID 35651701, 2022). "The expressions of IGF-1/IGF-1R share negative correlation with TMB and MSI in most cancer types, which means high expression of IGF-1/IGF-1R indicates immunosuppression." (PMID 34804946, 2021). "Although the EGF-activated PI3K/Akt/CREB signaling axis upregulates SGLT1 expression and enhances glucose uptake in intestine epithelial cells, the tyrosine kinase activity of EGFR or IGF1R and Akt signals are not needed for SGLT1 upregulation in cancer cells." (PMID 34155348, 2021). "Unexpectedly, the IGF1R/PCNA colocalization was absent in most metastatic lesions, neoadjuvantly treated tumors (with poor treatment response) and most cancer cell lines." (PMID 32701997, 2020). "The performance of IGF-1R is critical in the growth and migration of cells, therefore it is not startling that the signaling of IGF-1 strongly props cancer establishment." (PMID 30881358, 2019). "It is likely that cancers that are reliant on IGF-1R signalling will exhibit the greatest benefit from co-targeting, which again highlights the lack of biomarkers for IGF-1R activity as a key challenge." (PMID 27472395, 2016). "In this study we confirmed that the PPP-induced G2/M arrest is independent of IGF-1R because it occurred in igf1r-/- (R-) MEFs and after IGF-1R downregulation using siRNA in cancer cell lines." (PMID 25268741, 2014). "In conclusion, the exercise contributes to the reprogramming of intermediate metabolism in cancer cells/tissue through the activation of AMPK, IGF-1 and IGF-1R resulting in a potential nonpharmacological adjuvant in the management and treatment of some types of cancer including LC." (PMID 39555455, 2024). "Meanwhile, the IGF-1R signaling can be enhanced by non-receptor tyrosine adhesion kinase FES-related (FER) to facilitate cooperative growth and adhesion signaling that potentially contributing to cancer progression." (PMID 38665430, 2024). "Other studies have found that estrogen can bind to IGF-1R and exert non-genetic transcriptional effects through the Ras/MAPK signaling pathway and that the Ras/MAPK pathway could lead to the cancer recurrence." (PMID 34917501, 2021).
cancer (continued). "E-cadherin, which is often repressed in migratory cancer cell lines and upon EMT, especially in triple negative breast cancer cells, is readily detectable in a complex with the IGF-1R at sites of cell–cell contact in cancer cells with no or low migratory capacity." (PMID 33584548, 2020). "However, under pathological conditions, such as cancer, STAT proteins are constitutively phosphorylated by RTKs, including epidermal growth factor receptor (EGFR) and IGF1R, or non-RTKs, such as c-Src and JAK, thereby driving metastatic disease." (PMID 30013043, 2018). "IGF-1R is a cell surface receptor tyrosine kinase (RTK) that is substantially expressed in malignant tissues and plays a crucial role in growth and survival of cancer cells but is not absolutely required for normal cell growth." (PMID 21423728, 2011). "Given that p-Src is induced by different types of growth factors, hormone, and integrin receptors in cancer cells, the lack of its inhibition by MH suggests that the latter does not interfere with ligand binding to multiple receptor types, including PDGF-R, EGF-R, FGF-R, VEGF-R, and IGF-1R." (PMID 31491838, 2019). "We and others have shown that inhibition of mTORC1 relieves negative feedback on upstream activators, including IRS-1, IGF-1R, human epidermal growth factor receptor 3 (HER3), and PI3K, which may subsequently promote cell survival and antagonize the anti-cancer effects of mTORC1 inhibitors." (PMID 29507656, 2018). "Thus, IGF-1R levels alone will not necessarily determine cancer cell responses to IGF-1 and anti-IGF-1R therapies, as IGF-1R activity and downstream signaling are influenced by adhesion signals and activation of other signaling pathways, which are discussed further below." (PMID 26191041, 2015). "Furthermore, activated IGF1R has been recently shown to translocate to the nucleus in both non-malignant tissues and cancers, although it remains to be determined whether IRS1 and IGF1R interact in this subcellular location." (PMID 22558377, 2012).